SIAH1 (siah E3 ubiquitin protein ligase 1)
Description:
E3 ubiquitin-protein ligase that mediates ubiquitination and subsequent proteasomal degradation of target proteins. E3 ubiquitin ligases accept ubiquitin from an E2 ubiquitin-conjugating enzyme in the form of a thioester and then directly transfers the ubiquitin to targeted substrates. Mediates E3 ubiquitin ligase activity either through direct binding to substrates or by functioning as the essential RING domain subunit of larger E3 complexes. Triggers the ubiquitin-mediated degradation of many substrates, including proteins involved in transcription regulation (ELL2, MYB, POU2AF1, PML and RBBP8), a cell surface receptor (DCC), the cell-surface receptor-type tyrosine kinase FLT3, the cytoplasmic signal transduction molecules (KLF10/TIEG1 and NUMB), an antiapoptotic protein (BAG1), a microtubule motor protein (KIF22), a protein involved in synaptic vesicle function in neurons (SYP), a structural protein (CTNNB1) and SNCAIP. Confers constitutive instability to HIPK2 through proteasomal degradation. It is thereby involved in many cellular processes such as apoptosis, tumor suppression, cell cycle, axon guidance, transcription regulation, spermatogenesis and TNF signaling. Has some overlapping function with SIAH2. Induces apoptosis in cooperation with PEG3 (By similarity). Upon nitric oxid (NO) generation that follows apoptotic stimulation, interacts with S-nitrosylated GAPDH, mediating the translocation of GAPDH to the nucleus (By similarity). GAPDH acts as a stabilizer of SIAH1, facilitating the degradation of nuclear proteins (By similarity). Mediates ubiquitination and degradation of EGLN2 and EGLN3 in response to the unfolded protein response (UPR), leading to their degradation and subsequent stabilization of ATF4 (By similarity). Also part of the Wnt signaling pathway in which it mediates the Wnt-induced ubiquitin-mediated proteasomal degradation of AXIN1.
Synonyms: hSIAH1; BURHAS; SIAH1A
Tractability: PROTAC: ubiquitination databases record sites on it.
Gene: Protein-coding gene on chromosome 16 (48,356,364 to 48,448,402, reverse strand). Ensembl gene ENSG00000196470.
Subcellular location: Cytoplasm; Nucleus
Subcellular location (Human Protein Atlas): Mitochondria; Nucleoplasm
Pathways (Reactome):
Developmental Biology: Netrin-1 signaling
Immune System: Antigen processing: Ubiquitination & Proteasome degradation
Metabolism of proteins: Amyloid fiber formation
Gene Ontology:
Molecular function: identical protein binding; protein binding; ubiquitin protein ligase activity; ubiquitin-protein transferase activity; zinc ion binding; ubiquitin conjugating enzyme binding
Biological process: canonical Wnt signaling pathway; positive regulation of apoptotic process; positive regulation of intrinsic apoptotic signaling pathway; proteasome-mediated ubiquitin-dependent protein catabolic process; protein catabolic process; ubiquitin-dependent protein catabolic process; amyloid fibril formation; anatomical structure morphogenesis; apoptotic process; axon guidance; nervous system development; neuron apoptotic process; protein destabilization; protein ubiquitination; regulation of apoptotic signaling pathway
Cellular component: beta-catenin destruction complex; nucleoplasm; cytoplasm; cytosol; nucleus; early endosome
Genetic constraint (gnomAD): Loss-of-function variants: 2 observed, 21.13 expected, observed/expected ratio (o/e) 0.0947, 90% interval 0.038 to 0.3. The upper end of that interval is the gene's LOEUF score, 0.3, which puts it in group 1 of 6, group 1 being the genes least tolerant of losing a copy. Missense variants: 119 observed, 376.2 expected, observed/expected ratio (o/e) 0.32, 90% interval 0.27 to 0.37. Synonymous variants: 118 observed, 132.49 expected, observed/expected ratio (o/e) 0.89, 90% interval 0.77 to 1.04.
Homologues: Orthologues: chimpanzee SIAH1 (100% identical), guinea pig SIAH1 (100% identical), macaque SIAH1 (100% identical), rabbit SIAH1 (100% identical), dog SIAH1 (99% identical), mouse Siah1a (99% identical), pig SIAH1 (99% identical), rat Siah1 (99% identical), tropical clawed frog siah1 (99% identical), mouse Siah1b (98% identical), zebrafish siah1 (98% identical), Caenorhabditis elegans siah-1 (67% identical). Paralogues in human: SIAH2 (79% identical), SIAH3 (38% identical), ZSWIM9 (23% identical).
Diseases named in the same sentence as SIAH1 in open-access papers:
SIAH1 is named in the same sentence as 59 diseases in open-access papers, as found by Europe PMC text mining. Sharing a sentence is not in itself a finding about the gene and the disease. The quoted sentences say what the papers report.
breast carcinoma (19 papers, 2010 to 2025). "In breast cancer tissue from patients, the downregulation of Bim expression has been associated with breast cancer progression, in conjunction with downregulation of SIAH1 expression." (PMID 22429491, 2012). "In search for novel strategies to enhance radiosensitivity of breast cancer, we investigated the role of Siah1 and its related variant Siah1L on the radiation response of SKBR3 and MCF-7 breast cancer cells using different approaches." (PMID 20682032, 2010). "We found that gain-of-function for Siah1, and especially its splice variant Siah1L, sensitized SKBR3 breast cancer cells to the cytotoxic effects of IR while siRNA for Siah1 decreased radiosensitivity in MCF-7 breast cancer cells." (PMID 20682032, 2010). "We therefore investigated the effects of Siah1 and its splice variants on breast cancer cells following IR." (PMID 20682032, 2010). "We evaluated the effect of Siah1, its splice variants Siah1L and the Siah1 mutant with the RING finger deleted (Siah1ΔR) on radiosensitization of human breast cancer cells." (PMID 20682032, 2010). "The nuclear expression of SIAH1 has been associated with its oncoprotein properties in liver and breast cancers, although the mechanism behind its nuclear localization remains unclear." (PMID 39695138, 2024). "The survival analysis indicated that the higher expression of ARIH1, SIAH1, and UBR5 was associated with shorter OS in breast cancer patients, whereas the higher expression of SIAH2 correlated with prolonged survival." (PMID 40004017, 2025). "As documented, SIAH1 overexpression induced the apoptosis of cancer cells and inhibited the progression of cancer in many cancers, such as breast cancer and hepatocellular carcinoma." (PMID 35951361, 2022). "MiR-107 has been shown to promote human breast cancer cell proliferation, colony formation, migration and invasion and inhibit apoptosis by reducing SIAH1 expression." (PMID 35731831, 2022). "It has been documented that the overexpression of Siah1 in breast cancer cells and hepatocellular carcinoma cells induces apoptosis of cancer cells and inhibits the progression of cancer." (PMID 32082080, 2020). "Congruently, an inverse correlation between miR-944 and SIAH1 protein expression was found in breast cancer cells." (PMID 27377268, 2016). "Our data provided evidences about the role of miR-944 as a novel upstream negative regulator of PTP4A1 and SIAH1 and contributed for the understanding of the molecular mechanisms controlling cell migration and invasion in breast cancer." (PMID 27377268, 2016). "On the contrary, SIAH proteins (especially SIAH1) have been found to act as a tumor suppressor in breast cancer, gastric tumors and liver cancer." (PMID 26580787, 2015). "In an effort to define the significance of expression of Siah1 on the biological behaviour of breast cancer, we performed cell invasion study with a modified Boyden chamber assay." (PMID 20682032, 2010). "Our results reveal for the first time how overexpression of Siah1L and Siah1 can determine radiosensitivity of breast cancer cells." (PMID 20682032, 2010). "Siah1 has been studied for use in the therapy of human breast cancer and a number of different genetically-engineered Siah1 variants have been constructed in an effort to enhance chemotherapy efficacy." (PMID 20682032, 2010). "Our data are similar to a recent study which demonstrated increased proliferation, decreased apoptosis and increased invasion of Siah1 siRNA in MCF-7 breast cancer cells." (PMID 20682032, 2010). "The Siah1 gene is located at 16q12.1, and it is reported that the expression of Siah1 is often reduced or absent in various types of human cancers, including bladder cancer, lung cancer, breast cancer and hepatocellular carcinomas." (PMID 32082080, 2020). "In addition, targeted silencing of SIAH1 using shRNAs confirmed the role of this protein in breast cancer cells migration." (PMID 27377268, 2016).
breast carcinoma (continued). "Finally, SIAH1 gene silencing by RNA interference significantly impaired cell migration of breast cancer cells." (PMID 27377268, 2016). "In a previous study, we demonstrated that under hypoxic conditions, HIF-1 increased transcription of the WWTR1 gene encoding TAZ and the SIAH1 gene encoding a ubiquitin ligase that triggers degradation of LATS2, a negative regulator of TAZ nuclear localization in breast cancer cells." (PMID 26059435, 2015). "The status of Siah1 and Siah1L was analysed in five breast cancer cell lines." (PMID 20682032, 2010). "Another major finding of this study is that transfection with Siah1 and Siah1L could suppress SKBR3 breast cancer cell invasiveness while Siah1 siRNA potently increased invasiveness in MCF-7 cells." (PMID 20682032, 2010). "Taken together these observations suggest that SIAH-1 could play a similar role in breast carcinoma than in HHC cells depending on its expression level and sub-cellular localization." (PMID 20144232, 2010). "Notably, functional inhibition of Siah1 by siRNA upregulated Tcf/Lef activity in breast cancer cells, in accordance to previous reports." (PMID 20682032, 2010). "Importantly, the increased clonogenic survival of MCF-7 cells detected after silencing of Siah1 post-IR highlights the key role of Siah1 in determining response of breast cancer cells to radiotherapy." (PMID 20682032, 2010). "Furthermore, we analysed the impact of Siah1 overexpression on the biologic behaviour of breast cancer cells by employing invasion and Tcf/Lef reporter studies." (PMID 20682032, 2010). "We also reported that over-expression of SIAH-1 in the epithelial breast cancer cell line MCF-7 blocked cellular growth by altering the mitotic process, predominantly during nuclei separation and cytokinesis, leading to multinucleated giant cell formation and tubulin spindle disorganization." (PMID 20144232, 2010). "The demonstration that HIF-1 mediates increased expression of TAZ and its positive regulator SIAH1 is conceptually similar to our finding that HIFs mediate the expression of Rho Kinase 1 and its positive regulator Rho A to stimulate the motility of hypoxic breast cancer cells." (PMID 25587023, 2014). "It is worth noting that in this study, 8 (ACTR3, ARF4, PGRMC1, RPS23, WDR12, ACTR2, SIAH1, and RPS27L) of 12 hub genes are related to cancers, such as lung cancer, epithelial ovarian cancer, gastric cancer, glioblastoma, breast cancer, and esophageal cancer." (PMID 33391181, 2020). "Our results pointed out that miR-944 is a novel upstream negative regulator of SIAH1 and PTP4A1 genes and provided for the first time evidence for its functional role in migration and invasion of breast cancer cells." (PMID 27377268, 2016). "In another study addressing the role of SIAH1 and SIAH2 in a syngeneic model of breast cancer, the authors observed that blockade of SIAH-substrate binding site resulted in reduced tumor growth and angiogenesis." (PMID 26580787, 2015). "The expression of mRNA encoding SIAH1, but not SIAH2, was also increased under hypoxic conditions in breast cancer cell lines." (PMID 25587023, 2014). "Analysis of gene expression data from human breast cancers revealed that SIAH1, but not SIAH2, mRNA expression showed a significant positive correlation with the expression of multiple HIF target genes." (PMID 25587023, 2014). "Comparison of the paired normal and tumoral samples from patients, revealed that in 19 of 25 cases (76%), the level of SIAH-1 mRNA was reduced in breast cancer tissues compared to their corresponding non-cancerous breast tissue." (PMID 20144232, 2010). "In line with previous report, MCF7 breast cancer cells exhibited strong expression of Siah1 and Siah1L, whereas BT-20, MDA-MB-231, SKBR3 and ZR75-1 breast cancer lines lacked any expression of Siah1 and Siah1L analysed." (PMID 20682032, 2010).
breast carcinoma (continued). "In addition, our data pointed out that knockdown of gene expression by miR-944 could represent a molecular tool to specifically inhibit relevant druggable targets such as SIAH1 and PTP4A1 in breast cancer." (PMID 27377268, 2016). "Siah1 and Siah1L mRNA expression was absent in four of five breast cancer cells lines analysed." (PMID 20682032, 2010). "Our results suggest that gene therapeutic or pharmacological approaches enhancing Siah1 and Siah1L in tumors with absent expression of these genes could increase the therapeutic ratio for breast cancer and have important implications for the development of novel strategies in radiotherapy." (PMID 20682032, 2010). "Having found that SIAH1, but not SIAH2, mRNA increased under hypoxia in breast cancer cell lines, we next investigated whether SIAH1 gene expression is HIF-regulated." (PMID 25587023, 2014).
hepatocellular carcinoma (17 papers, 2010 to 2026). A malignant tumor that arises from hepatocytes. "PEG10 overexpression was reported to be associated with a mediator of apoptosis (SIAH1) resulting in decrease in cell death as in hepatocellular carcinomas." (PMID 28193232, 2017). "Inactivation of SIAH1 is associated with hepatocellular carcinoma (HCC) tumor progression." (PMID 33958005, 2021). "Similar results about SIAH-1 expression have been reported in hepatocellular carcinomas, indicating that SIAH-1 mRNA expression is frequently reduced in malignant tissues compared to normal tissues." (PMID 20144232, 2010). "It was also described using semiquantitative RT-PCR that SIAH-1 expression was lower in six hepatoma cell lines, compared to normal liver tissue." (PMID 20144232, 2010). "Our previous studies have demonstrated that seven in absentia homologue 1 (SIAH1), an E3 ubiquitin ligase, is downregulated in hepatocellular carcinoma (HCC) and regulates substrate ubiquitination." (PMID 41872127, 2026). "In patients with hepatocellular carcinoma (HCC), nuclear accumulation of SIAH1 was correlated with carcinogenesis, tumor proliferation and migration." (PMID 27377268, 2016). "For instance, SIAH-1 has been reported to positively and indirectly regulate FBP-3 (FUBP3), which primarily supports human hepatocellular carcinoma cell proliferation, suggesting a key role in cancer development." (PMID 32391054, 2020). "To date, SIAH-1 has been found to be widely distributed in human cell lines and tissues, including CRC, with a decreased expression in breast and hepatocellular cancer." (PMID 24195777, 2013). "Other data showed that SIAH-1 was highly expressed in the nucleus, and that transient expression of cytoplasmic SIAH-1 resulted in a marked increase in apoptotic cells in hepatocellular carcinoma cell lines." (PMID 20144232, 2010).
hepatocellular carcinoma (continued). "Data obtained from both HBV infection and HBx overexpression systems invariably exhibited an inverse correlation between Siah-1 and HBx levels in human hepatoma cells, irrespective of whether they were treated with ATRA." (PMID 37515144, 2023).
colorectal cancer (8 papers, 2020 to 2024). A primary or metastatic malignant neoplasm that affects the colon or rectum. "CK1ε enhanced AXIN1 degradation by the ubiquitin–proteasome pathway by promoting the interaction of E3 ubiquitin‐protein ligase SIAH1 with AXIN1 in colorectal cancer cells." (PMID 38419282, 2024). "Not only SIAH1 but also its homologs (Siah1 & Siah2) interacts with DCC (deleted in colorectal cancer) and subjects it to proteolysis through the ubiquitin-proteasome pathway." (PMID 33958005, 2021). "Overexpression of SIAH1 in colorectal cancer (CRC) led to the suppression of cellular proliferation and invasion of malignant cells." (PMID 33958005, 2021). "Our previous studies showed that miR-450-5p targeted the 3′-UTR (3′- Untranslated Region) of Siah1 to regulate the progression of colorectal cancer." (PMID 32082080, 2020). "In colorectal cancer, m6A methylation can induce the upregulation of lncRNA RP11 to modulate Siah1-Fbxo45/Zeb1 complex to promote the dissemination of tumor cells." (PMID 34295922, 2021). "The results from our research demonstrated that Siah1 interacts with AKT and YAP, and it catalyzes the K48 poly-ubiquitylation and proteasome degradation of AKT and YAP in colorectal cancer cells." (PMID 32082080, 2020).